DTYMK (deoxythymidylate kinase)
Diseases named in the same sentence as DTYMK in open-access papers (continued):
Sharing a sentence is not in itself a finding about the gene and the disease.
cancer (21 papers, 2013 to 2025). A tumor composed of atypical neoplastic, often pleomorphic cells that invade other tissues. "Genetic alteration of DTYMK in cancers included gene mutations, structural variants, amplification and deep deletion (homozygous deletion)." (PMID 35903153, 2022). "Through analysis, we found that augmentation of DTYMK expression was linked to poor prognosis in several types of cancer." (PMID 35903153, 2022). "In this work, DTYMK expression level was positively linked to TMB in approximately 20 kinds of cancers but negatively associated with TMB in THYM." (PMID 36094557, 2022). "According to the results of The Cancer Genome Atlas (TCGA), the expression of DTYMK increased and associated with a poor prognosis in several cancers." (PMID 34795209, 2021). "Furthermore, DTYMK expression levels are linked to the presence of immune cells within various cancer types." (PMID 40357400, 2025). "In both instances, heightened DTYMK levels were correlated with deteriorated overall survival, disease progression, and increased proliferation of cancer cells." (PMID 39195238, 2024). "The inhibition of DTYMK can potentially enhance cancer cell sensitivity to PARP1 inhibitors by disrupting pyrimidine metabolism and amplifying DNA damage in cancer cells." (PMID 39195238, 2024). "To elucidate DTYMK mRNA expression in human cancers, we first downloaded the pan-cancer RNA-seq data of DTYMK mRNA expression from TCGA and GTEx, and then eliminated these columns which contained only tumor samples." (PMID 36159971, 2022). "Through the use of the Cox regression model, we identified distinct expressions of DTYMK in a variety of survival markers; these findings revealed DTYMK as a potentially useful prognostic component of specific cancers." (PMID 36094557, 2022). "With only the TCGA database, Mann-Whitney U-test showed the mRNA expression of DTYMK was significantly upregulated in 18 cancer types, while only downregulated in KICH." (PMID 36159971, 2022). "Firstly, augmented DTYMK expression in multiple cancers needs to be confirmed in tumor tissues using different methods such as qPCR and immunohistochemistry." (PMID 35903153, 2022). "Using the CPTAC dataset from the UALCAN platform, DTYMK protein expression in several cancers was further validated." (PMID 35903153, 2022). "Our findings present novel insights into the functional status of DTYMK from a pan-cancer perspective, linking DTYMK expression with tumor prognosis and providing a potential therapeutic target for various cancers." (PMID 36159971, 2022). "In the present study, we determined the expression of DTYMK and its correlation with the clinicopathological characteristics and prognosis of patients from a pan-cancer perspective." (PMID 36159971, 2022). "In some cancers like bladder, blood, brain, breast, eye, lung, ovarian, skin and soft tissue cancers, elevated expression of DTYMK resulted in poorer prognosis." (PMID 35903153, 2022). "Our study further demonstrate that DTYMK is a prognostic marker in several cancer types, especially in LGG, LIHC, LUAD, and STAD." (PMID 35903153, 2022). "Many studies reported that the upregulation of DTYMK was correlated with poor prognosis in various cancers." (PMID 36159971, 2022). "This study, together with others, supports and strengthens the significance of DTYMK as a target for cancer therapy." (PMID 35903153, 2022). "It was found that higher DTYMK expression was correlated with shorter OS in cancers like ESCA (p = 0.0084), KIRC (p = 2.9e-06), KIRP (p = 0.014), LIHC (p = 1.2e-05), LUAD (p = 2.5e-05), and PAAD (p = 0.015)." (PMID 35903153, 2022). "“pyrimidine metabolism”, “purine metabolism” and “metabolic pathways” are critical pathways in which DTYMK functions in human cancers." (PMID 35903153, 2022). "The expression level of DTYMK was shown to have a positive correlation with DNAss and DNAss in almost all forms of cancers, including LUAD." (PMID 36094557, 2022).
cancer (continued). "Their effects on DTYMK expression should be noted considering its potential role in human cancers progression." (PMID 35903153, 2022). "The DTYMK expression was shown to have varying degrees of links to DNAss and RNAss among diverse kinds of cancer." (PMID 36094557, 2022). "In this study, we first explored the mRNA expression of DTYMK in 33 different cancer types using RNA-seq data from TCGA and integrated it with GTEx." (PMID 36159971, 2022). "Despite these discoveries, however, these studies only focus the evaluation of DTYMK on a few cancer types, and litter is known regarding the prognostic and immunological role of DTYMK in various cancers." (PMID 36159971, 2022). "Taken together, these results suggested that DTYMK was abnormally expressed in pan-cancer perspective." (PMID 36159971, 2022). "To further investigate the detailed underlying mechanisms of oncogenic role in tumor progression, we analyzed the expression profile of DTYMK at a single-cell level and its potential functional status in pan-cancer." (PMID 36159971, 2022). "The key immune checkpoints (CD274, CTLA-4, HAVCR2, LAG3, PDCD1, PDCD1LG2, SIGLEC15, and TIGIT) also had a significant relationship with DTYMK expression in approximately 20 kinds of cancers, except in MESO, PCPG, and UCS." (PMID 36094557, 2022). "Previous documents have reported that the deoxythymidylate kinase (DTYMK) genes were involved in the progression of cancers." (PMID 36094557, 2022). "To further explore DTYMK expression in human cancers obtained from different stages, we analyzed the relationship between DTYMK and cancer stages using GEPIA." (PMID 35903153, 2022). "To explore the expression profile of DTYMK at a single-cell level and its potential functional status in pan-cancer, we performed an analysis on CancerSEA." (PMID 36159971, 2022). "In this research, the relative expression and prognostic significance of the DTYMK gene in pan-cancer were investigated." (PMID 36094557, 2022). "First, we examined the possible link between DTYMK expression and the immune infiltration degree in pan-cancer." (PMID 36094557, 2022). "The upregulation of a number of rate-limiting enzymes in pyrimidine biosynthesis such as deoxythymidylate kinase (DTYMK), thymidylate synthase (TYMS), and thymidine kinase 1 (TK1) in HCC is associated with cancer stemness and poor prognosis." (PMID 33747521, 2021). "DTYMK is the kinase playing a key role in DNA synthesis via dTMP phosphorylation catalysis, and its overexpression is related to unfavorable prognoses in several types of human cancers (e.g., lung and liver cancer)." (PMID 39195238, 2024). "In addition, an association between cancer stemness, poor prognosis of HCC and up-regulation of key enzymes of pyrimidine biosynthesis, such as deoxythymidylate kinase (DTYMK), thymidylate synthase (TYMS) and thymidine kinase 1 (TK1), has been described." (PMID 37108625, 2023). "Furthermore, other rate-limiting enzymes, such as thymidylate synthase (TYMS), thymidine kinase 1 (TK1), and deoxythymidylate kinase (DTYMK), are upregulated in HCC and are associated with poor prognosis and cancer stemness." (PMID 36835122, 2023). "Upregulation of DTYMK predicted poor survival status in most cancer types in TCGA." (PMID 36159971, 2022). "Results confirmed that DTYMK was up-regulated in many human cancer." (PMID 36170019, 2022). "Our findings demonstrated that DTYMK may be a new biomarker for the prognosis and immunotherapy in various cancers." (PMID 36094557, 2022). "Given that DTYMK expression varied across human cancers and correlated to cancer stages and immune subtypes as well as immune cell infiltrations, it is conceivable that DTYMK might be a potential prognostic marker." (PMID 35903153, 2022). "Given this conception, the cancer types with high DTYMK expression level may benefit from treatment of immune checkpoint inhibitors." (PMID 36094557, 2022).
cancer (continued). "As such, DTYMK might affect cancer cell proliferation and this requires further in vitro characterization." (PMID 35903153, 2022). "shDTYMK02 was used to stably disrupt DTYMK expression in cancer cell lines." (PMID 35903153, 2022). "Our results strengthen the viewpoint that DTYMK is a promising therapeutic target for cancers." (PMID 35903153, 2022). "Nevertheless, the biological role of DTYMK in pan-cancer, especially in LUAD is still poorly unknown." (PMID 36094557, 2022). "Moreover, DTYMK expression was increased in the different cancer stages of LUAD, compared with the normal control group." (PMID 36170019, 2022). "Inhibition of DTYMK expression in cancer cells impeded cell migration in vitro." (PMID 35903153, 2022). "DTYMK might be served as a potential biomarker for diagnosis and poor prognosis in various cancer types." (PMID 36159971, 2022). "We found that DTYMK expression varied among cancer immune subtypes." (PMID 35903153, 2022). "Notably, our results indicated a distinct correlation between DTYMK expression and immune infiltration in cancers like LGG, LIHC, LUAD and STAD, suggesting a complex interplay between DTYMK and tumor immune response." (PMID 35903153, 2022). "The functions of DTYMK in cancer cells were also biologically validated in vitro." (PMID 35903153, 2022). "Based on DTYMK being abnormally expressed from a pan-cancer perspective, we speculated that DTYMK can be used as a diagnostic marker." (PMID 36159971, 2022). "DTYMK expression also differed in different molecular subtypes of cancers." (PMID 35903153, 2022). "Higher expression of DTYMK was correlated with shorter RFS in cancers including ACC (p = 0.00068), BLCA (p = 0.045), KIRP (p = 0.0069), LGG (p = 1.6e-05), LIHC (p = 0.011), LUAD (p = 0.0045), PAAD (p = 0.0086), PRAD (p = 0.0066), SKCM (p = 0.02), and UVM (p = 0.02)." (PMID 35903153, 2022). "Significant alteration of DTYMK expression was shown in 11 cancer types." (PMID 35903153, 2022). "It remains unclear whether DTYMK expression has the potential to predict outcome and immune cell infiltration in cancers." (PMID 35903153, 2022). "The variation of DTYMK expression in different subtypes was found in 19 cancers." (PMID 35903153, 2022). "In conclusion, DTYMK may affect the prognosis of various cancers and is related to immune infiltration." (PMID 36170019, 2022). "The role of DTYMK on immune infiltration into cancers remains unexplored." (PMID 35903153, 2022). "Our results showed that DTYMK expression significantly influenced the prognosis of some cancers." (PMID 35903153, 2022). "Only few studies reported on the role of DTYMK, particularly in cancer occurrence and progression." (PMID 34795209, 2021). "Few studies have reported on the role of DTYMK, particularly in cancer occurrence and progression." (PMID 34795209, 2021). "DTYMK was found to be highly expressed in Pan-Cancer Atlas, especially in HCC." (PMID 34795209, 2021). "After DTYMK knockdown, a stronger inhibitory effect on tumor formation rate (tumors formatted in only 3 in 10 mice in the sh-DTYMK group) and tumor growth speed (p = 0.039) was observed in transplanted carcinoma in nude mice." (PMID 34795209, 2021). "This is a direct evidence that DTYMK affects the occurrence and development of cancer through LKB1." (PMID 32953265, 2020). "With validations of experiments and HCC patients in multiple cohorts, we provided lines of evidence that TK1, TYMS and DTYMK the catalytic RLEs in pyrimidine biosynthesis play critical roles in cancer stemness and serve as potential therapeutic targets in poorly-differentiated HCC." (PMID 29100421, 2017). "In addition to this, we investigated whether there was a link between DTYMK expression and the OS rate for each of the 33 distinct cancers in TCGA." (PMID 36094557, 2022). "Therefore, DTYMK could be valuable as a marker for prognosis and immune infiltration in human cancers and may act as a valuable therapeutic target in these cancers." (PMID 35903153, 2022).
cancer (continued). "Afterward, we evaluated the link between DTYMK expression and key immune checkpoints (CD274, CTLA-4, HAVCR2, LAG3, PDCD1, PDCD1LG2, SIGLEC15, and TIGIT) expression levels in pan-cancer." (PMID 36094557, 2022). "In summary, the results of this analysis underscore the fact that DTYMK is upregulated in HCC and plays a key role in the progression of this cancer type." (PMID 35004265, 2021). "Reduced dTTP pools, evidenced by CDC8/DTYMK and CDC21/TYMS, can increase doxorubicin cytotoxicity in cancer cell lines." (PMID 31660150, 2019). "High DTYMK expression was positively or negatively correlated with immune cell infiltration, including B cell, CD8+ cell, CD4+ T cell, macrophage, neutrophil and dendritic cell, depending on the type of cancers." (PMID 35903153, 2022). "The correlation between DTYMK and the major histocompatibility complex (MHC), immune inhibitors, immune stimulators, chemokines, and receptors expressed in the tumor microenvironment (TME) were also inspected across 30 cancer types." (PMID 35903153, 2022). "However, the correlation between DTYMK expression and tumor-infiltrating immune cells in pan-cancer has not been studied." (PMID 36159971, 2022).
tumor (19 papers, 2013 to 2025). "Elevated DTYMK expression level was discovered in LUAD patients belonging to subtypes C1, C2, C4, and C6, illustrating that DTYMK might be implicated in the promotion of tumor progression." (PMID 36094557, 2022). "In addition, association among DTYMK gene and tumor immunogenic features was also explored." (PMID 36094557, 2022). "Our findings suggested that DTYMK expression is correlated with clinical prognosis, tumor progression and immune infiltrate." (PMID 36159971, 2022). "DTYMK expression was positively correlated with tumor purity and infiltrating levels of B cells, CD8+ T cells, CD4+ T cells, macrophage, neutrophil, and dendritic cells in LIHC." (PMID 36159971, 2022). "To increase the reliability of the DTYMK expression level, we carried out UALCAN to analyze the protein expression of DTYMK between tumor and normal tissues in CPTAC." (PMID 36159971, 2022). "Paired t-test analysis suggested that DTYMK expression was significantly upregulated in 15 tumor tissues and only downregulated in KICH." (PMID 36159971, 2022). "Together these results showed that DTYMK had a potential role in regulating tumor-infiltrating immune cells level to further affect the prognosis of those tumors." (PMID 36159971, 2022). "DTYMK expression was then compared between tumor tissues and normal controls by TIMER using data derived from the TCGA database." (PMID 35903153, 2022). "In our study, we found that DTYMK expression is correlated with tumor-infiltrating immune cell levels by TIMER in LGG, LIHC, LUAD, MESO, SKCM, and UVM." (PMID 36159971, 2022). "These analyses both confirmed that suppressing the expression of DTYMK markedly suppressed HCC tumor cell proliferation." (PMID 35004265, 2021). "Similar to the results in vitro, the tumor formation rate and growth speed were significantly inhibited after DTYMK knockdown in nude mice." (PMID 34795209, 2021). "These cells or appropriate controls were then subcutaneously implanted into BALB/c nude mice, and tumor growth was monitored over time, revealing that suppressing DTYMK expression markedly inhibited the ability of these HCC tumors to grow in vivo." (PMID 35004265, 2021). "After the knockdown of DTYMK, the proliferation of Hep3B and Huh7 HCC cells was significantly inhibited, while the growth of the tumor cells was partially restored after the addition of dTDP, which was the product of DTYMK." (PMID 34795209, 2021). "We additionally identified miR-148b-3p as a novel endogenous regulator of DTYMK that also controls DTYMK-mediated dTTP production in HCC tumor cells." (PMID 35004265, 2021). "Analyses of these publically available datasets revealed that DTYMK expression levels were significantly higher in HCC tumor tissues relative to healthy tissue samples." (PMID 35004265, 2021). "We additionally confirmed these findings by assessing DTYMK mRNA expression in 40 pairs of HCC tumor and paracancerous tissue samples, which confirmed that DTYMK expression was increased 1.6-fold in HCC tumors relative to healthy tissues." (PMID 35004265, 2021). "Together, these findings indicate that miR-148b-3p functions as a tumor suppressor in HCC that can suppress tumor cell proliferation and migration at least in part by inhibiting the expression of DTYMK." (PMID 35004265, 2021). "The impact of overexpressing DTYMK in tumor cells was partially reversed upon cellular transfection with miR-148b-3p mimics, providing conclusive evidence that DTMYK is a target of this miRNA." (PMID 35004265, 2021). "Knockdown of TK1, TYMS and DTYMK reduced capability of forming tumor spheroids as shown in results of microscopy and in assays of 2 serial passages." (PMID 29100421, 2017). "we found that expression of TK1, TYMS and DTYMK enhanced tumor sphere formation capability and increased ALDH1 positive populations in well-differentiated HCC cells." (PMID 29100421, 2017).